IRAK1 (interleukin 1 receptor associated kinase 1)
Diseases named in the same sentence as IRAK1 in open-access papers (continued):
Sharing a sentence is not in itself a finding about the gene and the disease.
glioma (continued). "Furthermore, a homograft nude mouse model was explored and mice transplanted with TRAF6/IRAK1-overexpressing glioma cells had shorter survival times while mice transplanted with glioma cells with miR-146a-5p overexpression or TRAF6/IRAK1 knockdown lived longer." (PMID 37391426, 2023). "Interestingly, knockdown of IRAK1 also significantly increased ROS levels in glioma cells." (PMID 37031183, 2023). "A study in glioma demonstrated that high levels of IRAK1 bound to and prevented the degradation of PRDX1, a major member of antioxidant enzymes, in glioma cells, leading to the suppression of autophagic cell death and development of radioresistance." (PMID 39451208, 2024). "IRAK1 knockdown increased PRDX1 degradation, reduced malignancy, and enhanced radiosensitivity of glioma both in vitro and in vivo." (PMID 39451208, 2024). "Therefore, IRAK1 may be a valuable therapeutic target for glioma." (PMID 38830885, 2024). "We next explored the correlation for IRAK1 expression with cGAS and STING based on glioma patients from TCGA datasets." (PMID 37031183, 2023). "To understand the role of IRAK1 in glioma radioresistance, we preliminarily calculated the RSI based on the expression profiling of glioma samples from the TCGA cohort." (PMID 37031183, 2023). "We then treated glioma cells with the proteasome inhibitor MG132 and found that IRAK1 silencing-mediated destabilization of PRDX1 was reversed by MG132." (PMID 37031183, 2023). "Herein, we for the first time reported that IRAK1 was a novel oncogene in LGG, capable of inhibiting cell apoptosis and promoting glioma malignancy in vitro and in vivo." (PMID 35211171, 2022). "Mechanistically, HNRNPC maintains the mRNA stability of IRAK1 in an m6A-dependent manner, resulting in activation of the mitogen-activated protein kinase (MAPK) signaling pathway, which was necessary for the malignant behavior of glioma." (PMID 38830885, 2024). "Low IRAK1 levels increased the OS of LGG and overall glioma patients indicating that IRAK1 might be the direct effector modulating the progression of glioma." (PMID 37391426, 2023). "The analyses indicated that glioma patients with high IRAK1 expression could not benefit from radiotherapy." (PMID 37031183, 2023). "However, the role of IRAK1 in glioma has not yet been defined." (PMID 37031183, 2023).
lung carcinoma (8 papers, 2013 to 2026). "RESULTS: Eight PANoptosis-related genes (DAPK2, CAV1, PDK4, IL3RA, NOTCH1, CHMP4B, IRAK1, and SFN) were identified as being significantly associated with lung cancer." (PMID 41760846, 2026). "Elevated expression of IRAK1 has been reported in a variety of tumors, including lung cancer, endometrial carcinoma, and HCC, and has been identified to be correlated with tumor aggressive and poor patient prognosis." (PMID 37031183, 2023). "IRAK1 is a serine/threonine-specific protein kinase that frequently expressed in solid tumors, including lung cancer." (PMID 35155573, 2022). "It has been shown TLRs pathway molecules such as IRAK1and TLR2 have important roles in neoplasm diseases and the significant upregulation of IRAK1 and its involvement in the development of solid tumors including lung cancer have been reported." (PMID 33765916, 2021). "In our previously published cancer genomics study TRAF2, another member of the TNF receptor associated factors, was highly significantly repressed by more then 80% but IRAK1 was unchanged in c-Raf transgenic lung cancers." (PMID 24265725, 2013). "IRAK1 has been proved as the therapeutic target for lung cancer." (PMID 27619757, 2016).
myelofibrosis (8 papers, 2018 to 2024). A partial or complete replacement of the bone marrow stroma by fibrous tissue. "By selectively inhibiting IRAK1, pacritinib demonstrates efficacy not only in myelofibrosis but also in several other diseases." (PMID 38792088, 2024). "Pacritinib is approved for myelofibrosis and inhibits IRAK1 and downstream activation from TLR4, though pediatric studies have not yet been completed." (PMID 37762291, 2023). "Pacritinib is an oral JAK2/IRAK1 inhibitor that was recently approved in the United States in February 2022 for patients with myelofibrosis (MF) who have a platelet count below 50 × 109/L." (PMID 36467816, 2022). "The safety profile of the novel oral JAK2/IRAK1 inhibitor pacritinib in patients with cytopenic myelofibrosis was described in the Phase 2 PAC203 and Phase 3 PERSIST‐2 studies." (PMID 36467816, 2022). "Pacritinib is a JAK2/FLT3 inhibitor with IRAK1 inhibiting capabilities, presently under clinical investigation for myelofibrosis and glioblastoma." (PMID 34355696, 2021). "IRAK1 may play a role in MPNs (polycythemia vera [PV], essential thrombocythemia [ET], and myelofibrosis) via inflammatory cytokines, such as IL-6 and IL-8, that are downstream products of the dysregulated NF-κB pathway." (PMID 30279971, 2018). "Unexpectedly, selective nanomolar IRAK1 inhibition was detected in a kinome-wide screening study for the JAK2/FLT3 inhibitor, pacritinib, which is in late stage development for patients with myelofibrosis (MF) and other myeloproliferative neoplasms (MPNs)." (PMID 30279971, 2018).
triple-negative breast carcinoma (8 papers, 2015 to 2024). An invasive breast carcinoma which is negative for expression of estrogen receptor (ER), progesterone receptor (PR), and human epidermal growth factor receptor 2 (HER2). "In particular, triple negative breast cancers have been associated with overexpression of IRAK1, and it is reported that inhibition of IRAK1, through the p38-MCL1 pathway, may reverse paclitaxel resistance." (PMID 27367721, 2016). "For instance, IRAK1 was characterized as a critical factor in metastasis and resistance to paclitaxel in triple-negative breast cancer (TNBC)." (PMID 38796478, 2024). "In triple-negative breast cancer, IRAK-1 regulates the expression of inflammatory genes by immune cells." (PMID 36359024, 2022). "In triple-negative breast cancer (TNBC), IRAK1 overexpression was found to positively correlate with poor prognosis and the mechanism of TNBC growth was suggested to be IRAK1/NF-κB-dependent." (PMID 37370720, 2023). "Deregulation/amplification at the IRAK1 locus might also not be a mechanism of choice via which tumors upregulate IRAK1 activity, though IRAK1 overexpression has been detected in several tumor types, with particularly convincing evidence for causality in triple-negative breast cancer." (PMID 31799178, 2019).
gastric cancer (7 papers, 2012 to 2025). A primary or metastatic malignant neoplasm involving the stomach. "Here, we combined patient clinicopathological data with COL4A1, SLC16A7 and IRAK1 to create a predictive nomogram for gastric cancer." (PMID 39669362, 2024). "Overexpression of miR-146a suppresses gastric cancer cell migratory and invasive capacities by downregulating IRAK1, whereas upregulated miR-146a-5p stimulates chemosensitivity of non-small cell lung cancer cells to cisplatin." (PMID 35193602, 2022). "COL4A1, SLC16A7 or IRAK1 are prognostic biomarkers in gastric cancer." (PMID 39669362, 2024). "Initially, we developed a gene signature related to lactylation to forecast the outcome of stomach cancer by analyzing genes with varying expressions, such as COL4A1, SLC16A7, and IRAK1." (PMID 39669362, 2024). "In this study, we found that in 85As2 cells, which were established from MKN45cl85 human gastric cancer cells, the TLR5 signaling pathway was activated with increased IRAK-1/4 expression compared to in the parent cell line." (PMID 30410674, 2018). "miR-146a targets IRAK1 in gastric cancer cells, but not TRAF6." (PMID 22992343, 2012).
Hyperglycemia (7 papers, 2020 to 2025). An increased concentration of glucose in the blood. "Research on DPN in mice has shown that hyperglycemia causes downregulation of miR-146a expression, which is inversely related to inflammatory IRAK1 and TRAF6 protein levels in dorsal root ganglion (DRG) neurons." (PMID 40151454, 2025). "Previous researches are in line with our results, and TLR4/IRAK1/TRAF6/NF-κB pathway was markedly activated under hyperglycemia." (PMID 36148071, 2022). "The elevated expression of IRAK1 and phosphorylated NF-κB p65 subunit (p-p65) proteins induced by hyperglycemia was attenuated by C66." (PMID 32092902, 2020). "Compared to sustained hyperglycemia, glycemic fluctuation led to further increase in IL-1β, TNFα, RANKL, TLR2/4, IRAK1, and TRAF6 mRNA expression in peri-implant gingival tissues." (PMID 34401982, 2021).
Arthritis (6 papers, 2018 to 2024). Inflammation of a joint. "For example, some studies have examined the potential associations of SNPs in IRAK1 and miRNA-146 and the development of arthritis." (PMID 35669566, 2022). "Genetic association studies have examined the potential role of SNPs in IRAK1 and miRNA-146 as risk factors for the development of arthritis, with rheumatoid arthritis most often examined." (PMID 30279971, 2018). "The serum transfer model of arthritis revealed a potentially novel role of IRAK1 for disease development and neutrophil chemoattraction exclusively via its activity in nonhematopoietic cells." (PMID 35801586, 2022). "To address how IRAK1 signaling affects articular expression of IL-1β, we sought to identify the IL-1β–producing cell types during the early phase of arthritis." (PMID 35801586, 2022). "Since both hematopoietic and nonhematopoietic cells express IRAK1, we examined which cellular compartment supported IRAK1-dependent arthritis." (PMID 35801586, 2022). "This study has shown that miR-146a KO mice suffer more severe gouty arthritis than WT mice and has indicated that miR-146a-deficient mice lose the repression of TRAF6 and IRAK1, leading to enhanced production and secretion of pro-IL-1β." (PMID 29544526, 2018). "Moreover, evidence suggested that anti-IRAK1 exhibited unusual activity in a murine arthritis model." (PMID 35669566, 2022). "IRAK1 function drives serum-induced arthritis via neutrophil recruitment." (PMID 35801586, 2022). "An agent structurally similar to pacritinib with selective anti-IRAK1 activity, SB1578, has been shown to have remarkable activity in a murine collagen- induced arthritis model." (PMID 30279971, 2018). "With that, our data suggest that inhibition of IRAK1 kinase function is likely not sufficient for arthritis treatment, and that development of a drug that degrades IRAK1 protein may be of more merit." (PMID 35801586, 2022). "IRAK1 in nonhematopoietic cells is essential for the development of arthritis." (PMID 35801586, 2022). "With IRAK1’s involvement in IL-1R signaling and subsequent neutrophil recruitment in the TMPD model, we hypothesized that a similar effect may be evident in the IL-1–dependent K/BxN model of serum transfer arthritis." (PMID 35801586, 2022).
lupus nephritis (6 papers, 2013 to 2026). Glomerulonephritis in the context of systemic lupus erythematosus. "JP inhibits macrophage IRAK1/ NF-κB signaling, attenuates lupus nephritis by activating renal FXR to suppress TGF-β1/α-SMA-driven fibrosis, and mitigates oxidative damage via Nrf2 activation." (PMID 41981676, 2026). "An additional six genes showed an association with lupus nephritis with p <0.001 (PMS2, TNIP1, CARD11, ITGAM, BLK and IRAK1)." (PMID 24386384, 2013). "Our results support the notion that IRAK1 and/or IRAK4 are attractive targets for the development of drugs to prevent, and perhaps treat, lupus nephritis and other autoinflammatory diseases caused by the decreased ability of ABIN1 or other proteins to restrict the strength of MyD88 signaling." (PMID 27807192, 2016). "Suppression of IRAK-1 in these animals prevented lupus nephritis suggesting IRAK-1 is a downstream target of the regulatory action of ABIN1 in the NF-κB signaling pathway and perturbation of IRAK-1 expression may counteract the inhibitory action of ABIN1 in NF-κB activation." (PMID 33297945, 2020).
nasopharyngeal carcinoma (6 papers, 2022 to 2024). A carcinoma arising from the nasopharyngeal epithelium. "Moreover, IRAK1 induces chemoresistance in nasopharyngeal carcinoma through the IRAK1–S100A9 axis." (PMID 39451208, 2024). "In addition, pacritinib has also been reported to reduce chemotherapy resistance in nasopharyngeal carcinoma, mainly by regulating the phosphorylation level of IRAK1, thereby inhibiting the expression of S100A9 and reducing the patients with nasopharyngeal carcinoma resistance to paclitaxel." (PMID 35669566, 2022).
Obesity (6 papers, 2015 to 2025). Accumulation of substantial excess body fat. "We previously showed that the elevated adipose gene expression of TLR4, TLR2, and MyD88 in people with obesity/T2D was associated with the IRAK1 gene expression." (PMID 36552771, 2022). "The data have clinical significance as interventions causing IRAK-1 suppression may alleviate meta-inflammation in obesity/T2D." (PMID 26312071, 2015). "We next assessed whether the obesity-associated changes in the adipose tissue expression of IRAK-1 mRNA resonated with plasma levels of these markers." (PMID 26312071, 2015). "Immunohistochemistry analysis showed that TLR4, IRAK1 and NF-kB were significantly upregulated in individuals with obesity." (PMID 36552771, 2022). "AT-SRA1 expression was independently predicted by TLR3/TLR7 and IRAK1 in those with obesity and by TLR3/TLR9 in individuals with T2D." (PMID 36552771, 2022). "Our data further show that TLR3/TLR9 expression was associated independently with the expression of SRA1 in individuals with T2D, while TLR3, TLR7 and IRAK1 were identified as the independent predictors of adipose SRA1 expression in individuals with obesity." (PMID 36552771, 2022). "In the present study, we have identified IRAK-1 as a tissue marker of meta-inflammation in obesity by using gene expression analysis in the subcutaneous adipose tissue." (PMID 26312071, 2015). "This increase in the IRAK-1 gene expression correlated positively with clinical indicators of obesity such as BMI (r = 0.45; P = 0.001) and fat % (r = 0.36; P = 0.01)." (PMID 26312071, 2015). "The present data suggest that the increased IRAK-1 expression may be an additional biomarker for the adipose tissue inflammatory state in obesity." (PMID 26312071, 2015). "We hypothesized that obesity was an inducer or a positive modulator of IRAK-1 expression in the human white adipose tissue." (PMID 26312071, 2015). "IRAK-1 is a critical adapter protein of the TLR/IL-1R/MyD88 signaling pathway and obesity-associated changes in its expression remain unclear." (PMID 26312071, 2015). "The study has clinical significance as the approaches intending IRAK-1 suppression may improve metabolic complications in obesity or T2D." (PMID 26312071, 2015). "Based on consensus with both circulatory and local inflammatory signatures, IRAK-1 expression may be regarded as an additional tissue marker for meta-inflammation in obesity." (PMID 26312071, 2015). "The correlations of IRAK-1 gene expression were assessed against clinical markers of obesity, local proinflammatory mediators, monocyte/macrophage markers, systemic inflammatory markers, and more importantly, against upstream signaling components of the TLR/IL-1R/MyD88 pathway." (PMID 26312071, 2015). "The positive correlation between increased IRAK-1 gene expression and these markers in obesity indicates the concordance of the activation of TLR/IL-1R/MyD88 pathway and macrophage recruitment or colonization in the adipose tissue to induce or sustain inflammation." (PMID 26312071, 2015). "In the present study, we show that IRAK-1 gene expression was significantly elevated in the adipose tissues of obese and overweight non-diabetic individuals as compared with lean subjects and the changes correlated with clinical hallmarks of obesity including BMI and fat %." (PMID 26312071, 2015). "We asked whether obesity modulated the expression of IRAK-1 in the adipose tissue." (PMID 26312071, 2015). "The changes in adipose tissue expression of IRAK-1 in obesity/T2D remain unclear." (PMID 26312071, 2015). "Consistent with our finding of an increased expression of the mentioned markers, similar changes in the AT expression of MyD88, IRAK1, and IRF5 have been reported in individuals with obesity and/or type-2 diabetes." (PMID 36139454, 2022).
Obesity (continued). "In conclusion, our data show that the AT SRA1 expression correlates with TLRs-3,4,7,9, MyD88, NF-κB, and IRF5 expression in individuals with T2D and with TLR2, IRAK1, and IRF3 expression in individuals with obesity." (PMID 36552771, 2022). "In individuals with obesity (N = 64), TLR3, TLR7 and IRAK1 were detected as the independent predictors of adipose SRA1 expression." (PMID 36552771, 2022). "Our data show strong positive correlations between adipose IRF5 gene expression and that of TLR2, TLR7, TLR8, TLR9, MyD88, IRAK-1, and IRF3 in obesity." (PMID 31718015, 2019). "Furthermore, TLR3/TLR7/IRAK1 and TLR3/TLR9 were identified as independent predictors of AT SRA1 expression in individuals with obesity and T2D, respectively." (PMID 36552771, 2022). "Regarding expression of TLRs, their downstream signaling mediators and IRFs, adipose expression of TLR2 (p = 0.018), TLR3 (p = 0.010), TLR8 (p = 0.048), IRAK1 (p = 0.047), and IRF5 (p = 0.016) was significantly higher in participants with obesity compared to NW participants." (PMID 36552771, 2022).
Alzheimer disease (5 papers, 2013 to 2017). A progressive, neurodegenerative disease characterized by loss of function and death of nerve cells in several areas of the brain leading to loss of cognitive function such as memory and language. "IRAK1 is one of the major genes that drive postnatal nervous system development and is differentially regulated in Alzheimer’s disease and in stressed human astroglial cells." (PMID 28792504, 2017). "Experimentally proven targets of miR-146a include complement factor H (CFH), interleukin-1 receptor-associated kinase-1 (IRAK1) and TNF receptor-associated factor 6 (TRAF6), all associated with innate immunity and inflammatory pathways which are dysregulated in Alzheimer's disease." (PMID 24133413, 2013).
endometrial cancer (5 papers, 2022 to 2024). Primary or metastatic malignant neoplasm involving the endometrium (mucous membrane that lines the endometrial cavity). "IRAK1 is expressed at abnormally high levels in various tumors such as liver, breast, head and neck, and endometrial cancer." (PMID 38830885, 2024). "In a similar way, the inhibition of the epithelial-mesenchymal transition in endometrial cancer cells has been achieved via treatment with miR-192-5p expressed in TAM-derived EVs, via the inhibition of the Interleukin 1 Receptor Associated Kinase 1 (IRAK1)/NFκB signaling pathway." (PMID 37175226, 2023).
inflammatory bowel disease (5 papers, 2020 to 2023). A spectrum of small and large bowel inflammatory diseases of unknown etiology. "Studies about Inflammatory bowel disease (IBD) showed that overexpressing miR-146a inhibited TNF receptor-associated factor 6 (TRAF6) and IL-1 receptor-associated kinase 1 (IRAK1) expression in TNBS-induced colitis of rats." (PMID 32483483, 2020). "Finally, our evidence for a role of IRAK1 on synovial fibroblasts and emerging data on an IL-1β/neutrophil axis in patients with inflammatory bowel disease suggest that fibroblasts within other organs may show a similar phenotype." (PMID 35801586, 2022).